INS (insulin)
Diseases named in the same sentence as INS in open-access papers (continued):
Sharing a sentence is not in itself a finding about the gene and the disease.
Insulin resistance (continued). "In particular, hepatic insulin resistance is manifested by the blunted ability of insulin to activate its receptor kinase and its downstream targets, resulting in incomplete suppression of hepatic glucose production and therefore a clear hyperglycaemia." (PMID 27562101, 2016). "It seems that, rather than changes in incretin secretion, fasting hyperglucagonemia and consequent hyperglycemia play a role in reduced disposal of insulin, contributing to hyperinsulinemia and insulin resistance." (PMID 26942445, 2016). "GK plays a major role in glucose homeostasis, and insulin resistance reduces GK activity due to GK gene expression induced by insulin." (PMID 27792149, 2016). "The administration of DMY to the rats with HFD-induced insulin resistance reduces hyperglycemia, plasma levels of insulin, and steatosis in the liver." (PMID 27796348, 2016). "Stage 1 is described as ‘compensation’, where overweight or obese individuals with a degree of insulin resistance have to increase insulin secretion from beta-cells in order to maintain homeostasis." (PMID 27536890, 2016). "The physiological pregnancy induces insulin resistance (IR) which appears to result from a combination of increased maternal adiposity and the insulin-desensitizing effects of placental hormones." (PMID 26981539, 2016). "Noise exposure at 95 dB SPL caused insulin resistance in male ICR mice, which was prolonged with longer noise exposure and was likely related to the observed blunted insulin signaling in skeletal muscle." (PMID 27128844, 2016). "The problem is that the phenotype of insulin resistance is complex; for example, liver insulin receptor knockout mice (LIRKO) show hyperglycemia and hypolipidemia, due to total liver insulin signal deficiency." (PMID 27247938, 2016). "These authors attributed this finding to near normal insulin values (mean (SD); 9.3 (10.2) μU/mL) and low levels of insulin resistance (HOMAIR 1.8 (2.4))." (PMID 27274997, 2016). "Insulin resistance leads to elevating levels of circulating insulin, serum glucose, and inflammation, all factors which can fuel cancer progression, along with weight gain and poorer responses to cancer treatment." (PMID 26977321, 2016). "The investigators noted that the African cohorts had the greatest insulin resistance and the highest insulin response to glucose, while the converse was true for the East Asian cohorts, with the Caucasian groups being in the middle." (PMID 27830830, 2016). "Insulin resistance is the common denominator of several diseases including type 2 diabetes and cancer, and investigating the mechanisms responsible for insulin signaling impairment is of primary importance." (PMID 27149630, 2016). "Aging is a risk factor for T2D, a disease characterised by chronic hyperglycaemia resulting from impaired insulin secretion in combination with peripheral insulin resistance." (PMID 27029739, 2016). "Diabetes mellitus is a heterogeneous chronic metabolic disorder characterized by hyperglycemia as a common feature resulting from impaired insulin secretion, insulin resistance, or both." (PMID 27496100, 2016). "Obesity is a growing problem for patients with T1D given the vicious cycle of obesity-induced insulin resistance necessitating increasing insulin requirements to preserve glycemic targets, which leads to further weight gain." (PMID 27375900, 2016). "Mice heterozygous for PPARγ showed increased insulin sensitivity instead of the expected insulin resistance." (PMID 27483259, 2016). "The combined therapy of insulin plus metformin maintained glycemic control and insulin resistance similar to monotherapy with insulin." (PMID 27579154, 2016). "The Cort-HFD rats showed improved glucose tolerance, insulin secretion, hyperglycemia, hyperinsulinemia, and homeostatic model assessment of insulin resistance (HOMA-IR) values." (PMID 27929385, 2016).
Insulin resistance (continued). "The research findings showed that the HFD induced marked insulin resistance, as demonstrated by elevated blood glucose; insulin secretion; and impairments in insulin sensitivity, IRS/Akt-GLUT2 signaling, glycolysis, Krebs cycle, and gluconeogenesis." (PMID 27796348, 2016). "An interesting experiment shows how, in the presence of insulin resistance, there is up-regulation of the insulin/IGF-1 hybrid receptor expression in both, muscle and fat." (PMID 26733412, 2016). "In line with much of this, GR mRNA levels in the skeletal muscle of diabetic patients correlate strongly with the degree of insulin resistance, with a normalisation of GR expression following pharmacological treatment that improves insulin sensitivity." (PMID 27929385, 2016). "Overall, the role of insulin signaling on dopaminergic neurons in PD, in a background of T2DM-related insulin resistance, should be investigated to understand the underlying mechanisms." (PMID 27065205, 2016). "Neurite outgrowth stimulated by insulin also appears to be sensitive to higher doses of insulin suggestive of insulin resistance." (PMID 28066166, 2016). "Specifically, insulin transiently regulates tau phosphorylation in cultured neurons, while reduced insulin signaling increases tau phosphorylation both in cultured neuronal cells and in vivo models of insulin resistance and T2DM." (PMID 26858121, 2016). "Indeed, because mitochondrial dysfunction has been linked with the development of insulin resistance 61, 62, 63, 64, it is conceivable that decreased mitochondrial oxidative capacity may, at least in part, contribute toward the impaired insulin action observed in response to REDD1 deficiency." (PMID 27613400, 2016). "The pathology of type 2 diabetes (T2D) is characterized by impaired insulin secretion from pancreatic beta cells and impaired insulin action, known as insulin resistance (IR)." (PMID 26839898, 2016). "Serine phosphorylation inactivates the IRS, which reduces insulin signaling and triggers insulin resistance." (PMID 27617200, 2016). "Type 2 diabetes is a heterogeneous disorder characterized by peripheral insulin resistance, defects in insulin secretion, and β-cell apoptosis." (PMID 27656657, 2016). "As expected, the most marked reductions in insulin, insulin resistance (HOMA) and all measured lipids occurred between baseline (TP1) and immediately after the final two day restriction (TP2)." (PMID 27233359, 2016). "Despite presenting with no biological activity, once broken down to angiotensin II (AngII) via a consecutive action of renin and ACE, it can induce insulin resistance via a cross-talk mechanism between insulin and AngII signaling cascade." (PMID 26682227, 2016). "Some studies suggest that H2S inhibits insulin-induced glucose uptake and that excess of H2S contributes to adipose tissue insulin resistance in metabolic syndrome." (PMID 28042862, 2016). "Another selenoprotein, SeP, was also shown to be related to insulin resistance by aggravating insulin resistance through impairing insulin signaling." (PMID 27142520, 2016). "The TyG index has shown direct correlation with insulin resistance, as assessed by hyperinsulinemic euglycemic clamp or insulin-mediated glucose uptake." (PMID 27633375, 2016). "Angiotensin II activates renin-angiotensin-aldosterone system (RAAS) and affects the function of the pancreatic islets, resulting in islet fibrosis and reduced synthesis of insulin, and ultimately leading to insulin resistance." (PMID 27517947, 2016). "Type 2 diabetes mellitus (T2DM) is a metabolic disorder characterized by continuous deterioration of the insulin secretory capacity leading to insulin resistance and pancreatic β-cells apoptosis." (PMID 27152706, 2016). "Both fasting plasma insulin concentrations and the increase in plasma insulin 15 min following the administration of the glucose bolus were exacerbated in HF-fed mice, indicative of systemic insulin resistance." (PMID 26838266, 2016).
Insulin resistance (continued). "Exercise resulted in significant improvements on IGF-I, IGF-II, IGFBP-I, IGFBP-3, Insulin and Insulin resistance (P < 0.05)." (PMID 27562357, 2016). "Collectively, these data support a link between GLP‐1RA activation, OS reduction in insulin‐sensitive tissues, and overall reduction in insulin resistance." (PMID 27511983, 2016). "Insulin resistance and impaired insulin secretion are the two main pathophysiological mechanisms leading to type 2 diabetes." (PMID 27851812, 2016). "Both myo-inositol and its isomer d-chiro-inositol showed insulin mimetic effects in conditions of insulin resistance." (PMID 27807448, 2016). "While biometrics (Fig EV4B–D) were not drastically affected, fasting blood glucose and insulin were lower in diabetic mice, which led to an overall reduction in systemic insulin resistance (HOMA‐IR)." (PMID 27137487, 2016). "As LPS have previously been described as an inducer of insulin resistance, we next tested several key pathway molecules known to influence insulin sensitivity." (PMID 26751381, 2016). "Taking these results together, while fructose diet promoted insulin resistance (Fructose diet vs Control diet, p ≤ 0.05), strength training was able to return insulin sensitivity to normal values." (PMID 27487746, 2016). "Since insulin is involved in FOXO1 repression, FOXO1 is stimulated in insulin resistance condition where diminution of insulin signalling pathway prevails, leading to accelerated inflammatory response." (PMID 26956801, 2016). "Defects in insulin mediated activation of AKT can lead to insulin resistance and promote Type-2 diabetes." (PMID 26930065, 2016). "One of the hallmarks of T2DM is peripheral insulin resistance, in part due to unproductive insulin signaling through the insulin receptor." (PMID 27526875, 2016). "In parallel, the primarily increased insulin production will also increase insulin resistance, which further complicates the condition." (PMID 27729921, 2016). "In contrast, many previous studies support a relatively more important role of an insulin secretory defect, compared with insulin resistance, in type 2 diabetic subjects in East Asians, including Koreans and Japanese." (PMID 27275953, 2016). "Impaired insulin secretion and insulin resistance are the two major pathophysiological defects in type 2 diabetes." (PMID 27851812, 2016). "Insulin resistance impairs IR/PI3K/Akt/mTOR insulin signaling, promoting decreased GLUT4, AMPA, and NMDAR exportation to the membrane." (PMID 27547756, 2016). "Steroid-induced increases in insulin reflect the well-known induction of insulin resistance by corticosteroids." (PMID 27530235, 2016). "Blood glucose concentrations in fasting and fed RictorAdipoq-cre mice do not differ from controls; however, this requires approximately threefold higher plasma insulin suggesting insulin resistance." (PMID 27098609, 2016). "Although glucose levels and glucose tolerance only tend to be affected in males on phytoestrogen-free diets and in both sexes on high-fat diets following BPA exposure, T2D is characterized more by increased insulin levels and insulin resistance." (PMID 29051427, 2016). "HUA inhibited insulin signaling and induced insulin resistance in cardiomyocytes in vitro and in vivo, which is a novel potential mechanism of hyperuricemic-related cardiovascular disease." (PMID 26836389, 2016). "Intraperitoneal administration of 0.4 mg/kg globular adiponectin can improve insulin resistance and metabolic responses to insulin in male rats fed the high-fat diet via an AMPK- and nitric oxide-dependent mechanism." (PMID 27127795, 2016). "In Korean subjects, pathogenesis of isolated IFG was associated with insulin resistance and isolated IGT was associated with impaired insulin secretion." (PMID 26788515, 2016).
Insulin resistance (continued). "Insulin resistance (IR), characterized by the impairment of insulin action, is an important metabolic alteration which is frequently associated with obesity, and appears to be the primary mediator of metabolic syndrome (MetS)." (PMID 27101976, 2016). "Second, the insulin resistance phenotype itself is difficult to quantify, often relying upon indirect measures such as circulating insulin levels." (PMID 27312935, 2016). "It has been demonstrated that plasma adiponectin concentrations correlate negatively with insulin resistance (or correlate positively with insulin sensitivity) and fasting plasma insulin concentrations." (PMID 27189377, 2016). "Both myo- and d-chiro-inositol showed insulin mimetic effects in animal models of insulin resistance." (PMID 27807448, 2016). "Previous studies have demonstrated that OVX rats impaired glucose metabolism by increasing insulin resistance and deteriorating the regulation of insulin secretion in comparison to the sham-operated rats." (PMID 27216600, 2016). "Insulin resistance plays an important role in the development of dyslipidemia by contributing to an increase in the free fatty acid flux released from insulin resistant fat cells." (PMID 26770984, 2016). "Our novel finding on possible pathways of insulin resistance shows that elevated irisin might decrease fasting insulin level and then reduce the risk of insulin resistance indirectly, and adiposity might increase both fasting insulin and FPG levels and therefore induce insulin resistance." (PMID 27473122, 2016). "T2D is characterized by impaired insulin secretion arising from pancreatic beta-cell dysfunction and insulin resistance in hepatic, skeletal muscle, and other peripheral tissues, leading to decreased plasma glucose uptake." (PMID 27448167, 2016). "Retinol-binding protein 4, another adipokine upregulated in serum of insulin-resistance mice and humans, impairs insulin signaling in liver and muscle." (PMID 27148161, 2016). "The HCD mice displayed mild glucose intolerance and increased insulin sensitivity in comparison to glucose intolerance and insulin resistance when mice were placed on a HFD." (PMID 27992582, 2016). "In fact, serum concentration of IGFBP‐1, unlike IGFBP‐3 which binds 75–90% of circulating IGF‐I, is heavily influenced by the metabolic (i.e., insulin resistance, and insulin and glucagon levels) and nutritional (fasting and refeeding) state of the individual." (PMID 26443692, 2016). "In contrast, cohort B tended towards a less pronounced degree of HFD-induced insulin hypersecretion and peripheral insulin resistance." (PMID 27055260, 2016). "The main endpoints of two studies were impaired insulin metabolism and insulin resistance, but both studies also reported the incidence of T2D." (PMID 27869762, 2016). "The increase in NEFA flux induces insulin resistance in liver and skeletal muscles through direct or indirect (via triglyceride deposits) generation of metabolites and interfering with insulin signalling pathways." (PMID 27200209, 2016). "Type 2 diabetes mellitus has revealed mechanisms of insulin resistance that target either impairs in β-cell function or insulin insensitive action at adipose tissue, skeletal muscle, or liver tissues." (PMID 27242912, 2016). "In the event of insulin resistance in the liver, the liver sensitivity to insulin becomes low and blood glucose increases." (PMID 27187341, 2016). "Calculation of QUICKI index, which is a measure of insulin sensitivity indicated 12 weeks of HFD resulted in insulin resistance." (PMID 28005939, 2016). "Subsequently, maintaining the capacity of β-cells to secrete adequate amounts of insulin in response to multi-organ insulin resistance is paramount to preventing progression from prediabetes to type 2 diabetes." (PMID 27111219, 2016).
Insulin resistance (continued). "Adiposity (body fat percentage) is associated with increased fasting insulin levels and FPG (standardized path coefficient: 0.257 (p < 0.001) and 0.063 (p = 0.032), respectively), which then increases the risk of insulin resistance." (PMID 27473122, 2016). "Intraperitoneal glucose and insulin tolerance tests show that 5-HT treatment protected against the hyperglycemia and an elevation in insulin resistance observed in mice on the F diet." (PMID 26766570, 2016). "In particular, F-FOPS mice exhibited substantial increases in cecal propionate production, which were significantly correlated with reductions in fasting glucose and insulin levels, the index of insulin resistance, and plasma leptin levels." (PMID 26731528, 2016). "Insulin resistance (IR), contrary to insulin sensitivity (IS), refers to decreased response to insulin-mediated cellular actions." (PMID 27517054, 2016). "Hyperglycemic MPCCs became less sensitive to insulin’s effects on gluconeogenesis over time relative to the normoglycemic control (i.e. insulin resistance)." (PMID 27312339, 2016). "The insulin resistance observed in this study is related to the increase of abdominal fats and corroborate the insulin sensitivity index (Kitt) which was dramatically dropped in animal receiving enriched diet with oxidised palm oil and sucrose." (PMID 26841874, 2016). "In particular, insulin resistance (IR) occurs when insulin effect on muscle and fat tissues glucose uptake is defective and is not capable of inhibiting endogenous glucose production by the liver." (PMID 26697506, 2016). "Type 2 diabetes mellitus (T2DM) is a complex metabolic disease that is characterized by increased insulin resistance in the muscles and liver and/or decreased insulin secretion by pancreatic β cells." (PMID 26767080, 2016). "Insulin resistance is defined as inefficient glucose uptake and utilization in peripheral tissues in response to insulin stimulation." (PMID 27916833, 2016). "In vivo, feeding a MUFA-HFD was capable of significantly increasing insulin secretion in response to a glucose challenge in a mouse model of obesity-induced insulin resistance compared to SFA-HFD." (PMID 27128935, 2016). "Beyond its role in fatty acid biosynthesis, SCD1 is an important factor in the pathogenesis of lipid-induced insulin resistance with SCD1 deficiency up-regulating insulin-signalling components and glycogen metabolism in insulin-sensitive tissues." (PMID 27488580, 2016). "In these conditions, a reduction in insulin resistance has been described, and in some of the experimental models, a concomitant increase in insulin secretion was also observed." (PMID 27366200, 2016). "HOMA-IR is a commonly used model due to its simplicity, but ISI is a more complex assessment of insulin resistance and takes into account not only the fasting state, but concentrations of insulin and glucose during the OGGT." (PMID 27752263, 2016). "Typically, T2D is considered to be related to the combination of two metabolic defects, failure of pancreatic beta cells secreting sufficient insulin to compensate for the rising demand and insulin resistance." (PMID 27418144, 2016). "There are ethnic differences in the contribution of insulin secretory capacity and insulin resistance to plasma glucose elevation and glucose intolerance." (PMID 26788515, 2016). "In patients with prolonged or severe insulin resistance, however, the metabolic stress imposed upon their β-cells often initiates their apoptotic death, necessitating exogenous insulin administration." (PMID 27110686, 2016). "Human studies further revealed that insulin detemir overcomes cerebrocortical insulin resistance in obese subjects, and acutely intravenously applied insulin detemir induced changes in cortical activity in men." (PMID 27589235, 2016).